IL10 (interleukin 10)
Diseases named in the same sentence as IL10 in open-access papers (continued):
Sharing a sentence is not in itself a finding about the gene and the disease.
Sepsis (continued). "Despite the increase in inflammatory cytokines (IL-6, IFN-γ) and chemokine (MCP-1), elevated concentrations of IL-10 were detected, which functions as a temporal regulator of the transition from early reversible sepsis to the late phase of irreversible shock." (PMID 37621924, 2023). "Several studies have found that IL-10, along with a panel of pro-inflammatory cytokines, is expressed in severe sepsis, indicating a role in limiting excessive inflammation." (PMID 37627293, 2023). "Administering IL-10 within hours of the onset of sepsis suppresses TNF-α secretion and prolongs the therapeutic potential of rescue surgery." (PMID 37626822, 2023). "One study reported outcomes of IL-10 in the detection of sepsis, the sensitivity was 0.66 (95% CI: 0.46, 0.82; I2 = NA, p = NA) and the specificity was 0.79 (95% CI: 0.69, 0.87; I2 = NA, p = NA), respectively." (PMID 38027268, 2023). "Further analysis of the two sepsis clusters revealed inconsistent correlations of IL10 within the clusters." (PMID 38332910, 2023). "Recent studies have shown that CD28 agonism can prolong the survival of CLP-induced immunologically experienced sepsis mice via IL-10 released by T cells." (PMID 37261908, 2023). "Further, IL-10 and Foxp3 mRNA levels were also elevated in the cerebral cortex of sepsis survivor mice by the ITK inhibitor." (PMID 37175808, 2023). "The administration of MSC secretome gave an immunoregulatory effect in the form of a decreased expression of NF-κB p65 and p50, as well as a decrease in the serum TNF-α level, and an increased serum IL-10 level in rat model of sepsis." (PMID 37626822, 2023). "In our data too, while diminished IL-10 was observed in in-vitro conditions, higher levels were detected when RM were activated with the serum of mice in sepsis." (PMID 37696985, 2023). "Regarding S. aureus infection, PMNs are a major source of IL-10 during S. aureus-induced sepsis and accelerate disease progression, which is exacerbated by IFN-ɣ." (PMID 37179295, 2023). "Similar observations have been made in patients with sepsis, where overproduction of IL-10 appears to be a predictor of disease severity and adverse outcome." (PMID 35874678, 2022). "In a sepsis model using lipopolysaccharide (LPS), injection of the N-glycan upregulated serum IL-10, and suppressed pro-inflammatory IL-1β, TNF and IFN-γ." (PMID 36531987, 2022). "TNF-α can induce the expression of IL-6, IL-10, and IL-18, which can be used as an inflammatory marker for the development of sepsis." (PMID 35698642, 2022). "In Spearman correlation rank analysis, IL-6 was positively correlated with IL-10 (r = 0.654, p < 0.001), in which G- sepsis patients showed a stronger linear correlation between the two cytokines." (PMID 36544765, 2022). "On the basis of IL-10, IL-17, and PCT, a nomogram for predicting the risk of sepsis incidence is constructed." (PMID 35937269, 2022). "IL-10 showed positive correlations with the other six cytokines studied in patients with sepsis, and with IL-1β, TNF-α, IL-6, and IL-8 in patients with septic shock." (PMID 36536294, 2022). "Several studies have suggested that plasma cells as well as IL-10-producing Breg cells increase significantly in patients with sepsis and return to normal upon recovery." (PMID 36425582, 2022). "We revealed the engagement of mTOR target genes within H3K4me3-marked histone in neutrophils isolated from healthy individuals and stimulated in vitro with LPS or IL-10, as well as in neutrophils isolated from sepsis and periodontitis patients." (PMID 35757755, 2022). "IL-10 can also promote the proliferation of MDSCs in mice with sepsis and aggravate immunosuppression in mice with advanced sepsis." (PMID 36209190, 2022). "Through probable receptor competition, inhibition of S100A12 increased IL-10 production in LPS-stimulated PBMCs from both controls and patients with sepsis." (PMID 35723375, 2022).
Sepsis (continued). "This point was further strengthened by the decreased MHC-II expression and elevated IL-10 production of B cells that survived from sepsis-induced apoptosis, indicating an anergic profile." (PMID 35619710, 2022). "The importance of IL-10 production during sepsis has been well established in various sepsis models." (PMID 35563475, 2022). "The diffuse inflammation resulting from sepsis is responsible for a renal toxicity of the immune response, via pro-inflammatory cytokines (IL-6, IL-10, IL-1β, TNF-α) and a monocytic infiltration of renal parenchym." (PMID 37675005, 2022). "IL-1β, TNF-α, IL-10 and IL-6 are pro-inflammatory cytokines that play core roles in the pathogenesis of sepsis." (PMID 35225146, 2022). "Among the specific anti-inflammatory mediators enriched in sepsis, IL-1ra, IL-4 and IL-10 are the most studied." (PMID 36189302, 2022). "The results in this also showed that EA at ST36 inhibited the production of TNF-α, IL-1β, and IL-6 and increased IL-10 production in septic mice, suggesting its therapeutic effect on sepsis." (PMID 35722155, 2022). "For the anti-inflammatory cytokines (IL-4, IL-5, IL-10, IL-13), only the concentrations of IL-1RA showed a significant difference between children with sepsis compared to children with either clinical malaria or febrile controls." (PMID 35811678, 2022). "In fact, we have demonstrated that NET degradation has a protective effect as measured by the peripheral levels of IL-10 which is in accordance with what others have observe not only in stroke but in sepsis models." (PMID 35250974, 2022). "Giving that changes in inflammatory factors, including TNF‐α, IL‐1β, IL‐6, IL‐10, and iNOS, are a major characteristic of the sepsis model, we measured the inflammatory cytokines after LPS treatment." (PMID 35474613, 2022). "IL-10 levels can thus be considered as a predictive model for sepsis mortality in patients with burn injury." (PMID 36579591, 2022). "Hyperferritinemia is also related to a pro-inflammatory state in sepsis, with increases of interleukin (IL)-6, IL-18, Interferon γ, sCD163 and a decrease of the IL-10/tumor necrosis factor α ratio as quantitative markers of inflammation." (PMID 36614993, 2022). "Studies have found that IL-10 levels are significantly higher in burn patients who died from subsequent burn sepsis." (PMID 36579591, 2022). "For example, IL-10 contributes to impairment of the pulmonary antibacterial host response following sepsis." (PMID 35938048, 2022). "Polymorphisms in IL10 genes have also been associated with altered sepsis mortality and risk of ICU admission, highlighting IL10 as a potential therapeutic target." (PMID 36572854, 2022). "As a result of the study, the infection group had higher IL-10 levels than the sepsis group; this correlation was shown to be more pronounced in the sepsis group than it was in the infection group." (PMID 35937269, 2022). "In contrast, G+ NPMODS sepsis patients exhibited dispersed levels that implied an inconsistent relationship between IL-6 and IL-10 in such group of patients." (PMID 36544765, 2022). "To conclude, Th1/Th2 cytokines, especially IL-6 and IL-10, are comparably effective in discriminating G+/G- bacteria-induced sepsis in the PICU." (PMID 36544765, 2022). "The immunosuppressive IL-10 cytokine, whose levels increase significantly during later sepsis, promotes the Hotairm1-mediated shuttling of S100A9 protein to the nucleus in MDSCs." (PMID 35185915, 2022). "Based on the variation pattern of IL-6 and IL-10, we used combined indicators “IL-6 IL-10 ratio” and “IL-6 IL-10 differences” to further describe cytokine patterns among G+/G- sepsis patients." (PMID 36544765, 2022). "An immune cell-specific study has found that MMP9, ARG1, CXCL3, SOCS3, CCR7, and IL-10 are differentially expressed in T cells and monocytes from sepsis patients compared with healthy individuals." (PMID 35721566, 2022).
Sepsis (continued). "MDSCs obtained from early (3 days) CLP-sepsis appeared to express pro-inflammatory cytokines and nitric oxide while those isolated late (day 12) in sepsis expressed anti-inflammatory cytokines (IL-10) and TGFβ." (PMID 36532055, 2022). "have recently shown that upregulating the IL-10 production have beneficial effects in a mouse model of sepsis." (PMID 35246004, 2022). "The reactions of some pro inflammatory cytokines such as tumor necrosis factor-alpha (TNF-α), interleukin-6 (IL-6), and interleukin-10 (IL-10) have all been characterized in the situation of sepsis, surgical damage, and trauma." (PMID 35148750, 2022). "The infection subgroup Y (sepsis group = 1, infection group = 0) was used as the response variable, and IL-10 (X1), IL-17 (X2), and PCT (X3) were used as independent variables." (PMID 35937269, 2022). "These two cytokines, TNFα pro-inflammatory and IL-10 with pleiotropic effects immunity and inflammation, have also been observed to rise early in sepsis and in acute respiratory failure." (PMID 36548717, 2022). "Two pro-inflammatory mediators, IL-6 and IL-10, have been specifically identified as being involved in the development of renal lesions in murine models of sepsis." (PMID 37675005, 2022). "ELISA showed that the HMGB1 and IL-10 levels were higher in patients with sepsis than in healthy donors." (PMID 35983056, 2022). "For G- sepsis patients, the observed narrower confidence intervals (compared to G+ sepsis patients) in “IL-6 and IL-10 differences” proved the efficacy of using such indicator to describe the IL-6–IL-10 correlation." (PMID 36544765, 2022). "To increase overall performance for discriminating sepsis we combined CRP with IL-10 and found a greater AUC of 0.860 (Cl 95% 0.756-0.931), while increasing specificity (98%) but not sensitivity (75%)." (PMID 35582414, 2022). "The production of TNF-α, IL-10, and IL-12 from PBMCs was significantly increased after LPS stimulation of PBMCs from both controls and patients with sepsis." (PMID 35723375, 2022). "Several reports have shown that TNF-α, IL-6, and IL-10 can be used as criteria for evaluating the severity of sepsis, and that elevated levels of cytokines predict mortality in septic mice." (PMID 36743669, 2022). "Our study is the first to demonstrate that inhibiting S100A12 with neutralizing anti-S100A12 human antibody significantly increased TNF-α and IL-10 production in LPS-stimulated PBMCs from controls and patients with sepsis." (PMID 35723375, 2022). "In particular, IL-6, IL-8, and IL-10 are used to diagnose sepsis, to assess the level of inflammatory response and to help the prognosis." (PMID 36291031, 2022). "IL-6, IL-8 and IL-10 peak as soon as sepsis is suspected, while PCT and CRP react later, with concentration peaks at 8–16 and 16–24 h, respectively." (PMID 35626858, 2022). "We evaluated 8 cytokines and 8 adipocytokines in both sepsis and burns and concluded that resistin forms a network with IL-6, IL-8, IL-10 and MCP-1 by hierarchical clustering analysis based on Spearman correlation." (PMID 35784283, 2022). "Sorted MDSCs from sepsis patients showed increased IL-10, ARG1, and iNOS expression; however, a significant increase was observed in IL-10 compared to that in HCs (p = 0.016)." (PMID 35720398, 2022). "Almost all G- sepsis patients experience a marked elevation of IL-6 compared to IL-10 at admission, which was less commonly observed in the G+ sepsis group." (PMID 36544765, 2022). "In an initial phase of sepsis, this mouse model present a higher expression of IL-10 and CTLA-4 in Tregs, reduced tissue damage and promotion of macrophage polarization to an M2 phenotype induced by sepsis via Tregs." (PMID 35370925, 2022). "This view was further strengthened by the subsequent study, in which enhanced IL-10 production was noticed in circulating DCs from patients with sepsis." (PMID 35619710, 2022).
Sepsis (continued). "Significantly, a landmark study found that bone marrow mesenchymal stem cells can reduce sepsis mortality and improve organ function by reprogramming macrophages to express large amounts of IL10." (PMID 35015384, 2022). "Similar functions of IL-10 in suppressing T-cell proliferation, promoting Treg production, and limiting effector cytokine production are observed in patients with sepsis." (PMID 36209190, 2022). "Analysis of plasmatic cytokines showed that, in all mouse strains, sepsis was accompanied by increase of IL-1β, IL-6, IL-10, TNF-α and IFN-γ." (PMID 36119089, 2022). "Proinflammatory immune biomarkers such as IL‐6, IL‐8, and IL‐10 highlight the patient status at the beginning of sepsis." (PMID 36176597, 2022). "Addition of interleukin 10 (IL-10) in patients with sepsis activated the adaptive immune system by improving T-cell IFN-γ production but diminished the activity of the innate immune system by decreasing TNF-α production as well as surface expression of HLA-DR." (PMID 36703923, 2022). "Here, we found that KDM6A specific inhibitor GSK-J4 supports an exchange between H3K27me3 and H3K4me3 at Hotairm1 promoter in mouse and human MDSCs, thereby mediating the effect of other bioactive mediators of sepsis immunosuppression (e.g., IL-10)." (PMID 35185915, 2022). "IL-6 and IL-10 are comparably effective in discriminating G+/G- sepsis in pediatric intensive care unit (PICU) patients." (PMID 36544765, 2022). "As an example, the N-glycan from C. albicans ameliorates mouse sepsis through immunosuppressive cytokine IL-10." (PMID 36531987, 2022). "CD19hiFcγRIIbhi B cells secreted more IL-10, compared with CD19lowFcγRIIblow B cells, from both patients with sepsis and healthy donors." (PMID 35983056, 2022). "Isatou Baha 31et al., support that IL-10 drives the molecular path that generates MDSCs and enhances immunosuppression during late sepsis." (PMID 35280697, 2022). "Although cytokines were measured at early onset of sepsis, IL-6 and IL-10 were sufficient enough for the prediction of NPMODS, in which their optimal cutoff values outperform that observed in diagnosing G- sepsis." (PMID 36544765, 2022). "We also found that IL-17 increased, while IL-10 decreased, indicating that this study is in line with “excessive inflammatory response” in early stage of sepsis." (PMID 35528843, 2022). "In sepsis patients, MDSCs had increased IL-10, Arg1, and iNOS mRNA levels (p = 0.016, p = 0.043, and p = 0.045)." (PMID 35720398, 2022). "Circulating chemerin and CRP at sepsis onset outperformed procalcitonin, IL-6, IL-10 and suPAR in discriminating sepsis from septic shock." (PMID 35204801, 2022). "High levels of IL‐10 were recorded in severe COVID‐19 patients and found to be associated with the compensatory anti‐inflammatory response syndrome that may be responsible for a greater number of secondary infections (50%) and sepsis (100%) reported in survivors." (PMID 37521849, 2022). "IP-10 is associated with various inflammatory conditions such as autoimmune diseases, hemophagocytic syndromes and viral infections where its combination with phospholipase A2, or IL-10 were suggested for sepsis diagnosis." (PMID 36509812, 2022). "These three indices were shown to be superior to other laboratory indices in the diagnosis of early sepsis, with AUC values of IL-10, IL-17 and PCT and three combined tests over 80% and negative predictive values above 70%, respectively." (PMID 35937269, 2022). "Interferon-gamma (IFN-γ) and IL-10 were ascribed prognostic and predictive value for sepsis outcome and therapy, as a low IFN-γ/IL-10 ratio was predictive for positive hydrocortisone therapy response in septic shock patients." (PMID 35732880, 2022). "In the receiver operating characteristic (ROC) curves of the G- sepsis group, the area under the curve (AUC) value for IL-6 and IL-10 was 0.679 (95% CI 0.561–0.798) and 0.637 (95% CI 0.512–0.762), respectively." (PMID 36544765, 2022).
Sepsis (continued). "The percentage of IL-10-producing CD19+CD24hiCD38hi Breg cells in neonatal sepsis with good prognosis is also significantly increased compared with healthy controls." (PMID 36425582, 2022). "Distribution patterns of IL-6 and IL-10 in G+/G- sepsis patients were significantly different in both bloodstream and non-bloodstream infections (p < 0.05)." (PMID 36544765, 2022). "Spearman test proved the linear correlation between IL-6 and IL-10 (r = 0.654, p < 0.001), and their combination indicators (ratio and differences) were effective in identifying G- sepsis." (PMID 36544765, 2022). "Immunosuppressive IL-10 cytokine commonly supports sepsis-induced immunosuppression and its levels increase in mouse MDSCs as sepsis progresses to the later, protracted stage." (PMID 35185915, 2022). "Other studies showed that Cav1 coordinated and coupled with Notch1/HES1 in the liver tissue of LPS–induced septic mice, which promoted the production of IL–10 in macrophages, leading to inhibition of inflammation in a model of sepsis." (PMID 35911737, 2022). "A ginsenoside Rg6, which is known to have a strong anti-inflammatory activity, has also been reported to enhance the IL-10 secretion in LPS-induced sepsis model mice." (PMID 34451753, 2021). "Studies have implicated that overproduction of IL-1β, IL-6, TNF-α, and IL-10 in mice and humans is associated with sepsis, and IFN-γ expression is enhanced persistently in patients who die of sepsis." (PMID 34612675, 2021). "During the immunosuppressive phase of sepsis, IL-10 leads to suppression of macrophage cytokine secretion and decreased activity of macrophage and neutrophil functions." (PMID 35003518, 2021). "In the regulation of cytokine production, some cytokines had been proved to be beneficial for the control of sepsis, such as the anti-inflammatory cytokines of IL-1Ra, IL-4, IL-6, IL-10, IL-11, IL-13, IL-35, and TGF-β." (PMID 34938184, 2021). "IL-1b and IL-10 levels were significantly higher in patients who worsened than in those who improved only in the group of patients with sepsis with sufficient predictive value." (PMID 33917002, 2021). "Conversely, for patients that will present an IAI, IL10 level was higher from D1 to D7 in sepsis with a hospital-acquired primary infection than in community-acquired infection or other pathologies." (PMID 34795661, 2021). "The more severe cases of neonatal sepsis had higher expression levels of IL-10, especially in low birth weight infants with sepsis." (PMID 34676267, 2021). "Different doses of recombinant IL-10 are known to have differential influences on the survival of mice with sepsis." (PMID 33154574, 2021). "IL-10 also displays ambiguous behavior in murine neurotropic coronavirus encephalomyelitis and human sepsis through opposing effects on IFN-γ production." (PMID 33746948, 2021). "Monocytes from patients with sepsis had altered DNA methylation profiles compared to controls, with several hyper- and hypo-methylated CpG sites in monocytes from patients with sepsis correlating with increased constitutive production of IL-10 and IL-6." (PMID 33685492, 2021). "Reduced cytokine levels in sepsis, prevented acute lung injury and organ dysfunction, down‐regulated inflammation (IL‐10, IL‐6) and swiftly up‐regulated phagocytosis and bacterial killing." (PMID 34766151, 2021). "In a polymicrobial sepsis model, the protective effect of B1a B cells was also mediated by IL-10 produced by B1a B cells." (PMID 33801658, 2021). "These cells can secrete the anti-inflammatory factor IL-10 and suppress the excessive inflammatory response in early sepsis." (PMID 34335278, 2021). "The levels of cytokines IL-1β, IL-6, IL-8, MCP-1, and IL-10, and of plasminogen activator inhibitor 1 (PAI-1), were reported to be increased over the acute phase and that IL-6, IL-8, MCP-1, and IL-10 formed a cytokine network in the acute phase of sepsis." (PMID 34654467, 2021).